SLC12A6 (solute carrier family 12 member 6)
Description:
[Isoform 1]: Mediates electroneutral potassium-chloride cotransport when activated by cell swelling. May contribute to cell volume homeostasis in single cells. [Isoform 2]: Mediates electroneutral potassium-chloride cotransport when activated by cell swelling. May contribute to cell volume homeostasis in single cells (Probable). [Isoform 3]: Mediates electroneutral potassium-chloride cotransport when activated by cell swelling. May contribute to cell volume homeostasis in single cells (Probable). [Isoform 4]: Mediates electroneutral potassium-chloride cotransport when activated by cell swelling. May contribute to cell volume homeostasis in single cells (Probable). [Isoform 5]: Mediates electroneutral potassium-chloride cotransport when activated by cell swelling. May contribute to cell volume homeostasis in single cells (Probable). [Isoform 6]: Mediates electroneutral potassium-chloride cotransport when activated by cell swelling. May contribute to cell volume homeostasis in single cells (Probable).
Synonyms: KCC3; KCC3A; KCC3B; ACCPN; CMT2II
Tractability: Small molecule: a structure with a bound ligand is known; it belongs to a druggable protein family. Antibody: UniProt places it where antibodies can reach, with high confidence; its Gene Ontology location is reachable by antibodies, with high confidence; UniProt predicts a signal peptide or a membrane-spanning region. PROTAC: ubiquitination databases record sites on it; its protein half-life has been measured.
Gene: Protein-coding gene on chromosome 15 (34,229,784 to 34,338,060, reverse strand). Ensembl gene ENSG00000140199.
Subcellular location: Cell membrane; Basolateral cell membrane
Subcellular location (Human Protein Atlas): Cytosol; Vesicles
Pathways (Reactome):
Disease: Defective SLC12A6 causes agenesis of the corpus callosum, with peripheral neuropathy (ACCPN)
Transport of small molecules: Cation-coupled Chloride cotransporters
Gene Ontology:
Molecular function: potassium:chloride symporter activity; protein binding; chloride:monoatomic cation symporter activity; protein kinase binding; transmembrane transporter activity
Biological process: cell volume homeostasis; cellular hypotonic salinity response; monoatomic ion transport; potassium ion import across plasma membrane; potassium ion transmembrane transport; angiogenesis; cellular hypotonic response; chloride ion homeostasis; chloride transmembrane transport; chloride transport; potassium ion homeostasis; transmembrane transport
Cellular component: plasma membrane; apical plasma membrane; basolateral plasma membrane; membrane
Genetic constraint (gnomAD): Loss-of-function variants: 29 observed, 63.64 expected, observed/expected ratio (o/e) 0.46, 90% interval 0.34 to 0.62. The upper end of that interval is the gene's LOEUF score, 0.62, which puts it in group 2 of 6, group 1 being the genes least tolerant of losing a copy. Missense variants: 619 observed, 871.82 expected, observed/expected ratio (o/e) 0.71, 90% interval 0.66 to 0.76. Synonymous variants: 314 observed, 320.04 expected, observed/expected ratio (o/e) 0.98, 90% interval 0.89 to 1.08.
Homologues: Orthologues: chimpanzee SLC12A6 (99% identical), macaque SLC12A6 (99% identical), guinea pig SLC12A6 (99% identical), pig SLC12A6 (99% identical), dog SLC12A6 (99% identical), rabbit SLC12A6 (99% identical), mouse Slc12a6 (98% identical), rat Slc12a6 (97% identical), tropical clawed frog slc12a6 (77% identical), Drosophila melanogaster kcc (53% identical), Caenorhabditis elegans kcc-2 (45% identical), Drosophila melanogaster Ncc69 (24% identical), and 4 more. Paralogues in human: SLC12A4 (72% identical), SLC12A5 (66% identical), SLC12A7 (65% identical), SLC12A1 (26% identical), SLC12A2 (26% identical), SLC12A3 (25% identical), SLC12A9 (23% identical), SLC12A8 (13% identical).
Diseases named in the same sentence as SLC12A6 in open-access papers:
SLC12A6 is named in the same sentence as 60 diseases in open-access papers, as found by Europe PMC text mining. Sharing a sentence is not in itself a finding about the gene and the disease. The quoted sentences say what the papers report.
Andermann syndrome (7 papers, 2013 to 2022). "Inactivating mutations of the Slc12A6 gene encoding KCC3 are the cause of a complex neurological disease known as agenesis of the corpus callosum with peripheral neuropathy, also referred as Andermann syndrome (Online Mendelian Inheritance in Man (OMIM) 218000)." (PMID 24043619, 2013). "The SLC12 family is a nine-member gene family with three established associated human diseases: SLC12A1 (MIM No. 600839), SLC12A3 (MIM No. 600968), and SLC12A6 (MIM No. 604878), which cause Bartter, Gitelman, and Andermann syndromes, respectively." (PMID 34226616, 2021).
arterial hypertension (4 papers, 2016 to 2021). "KCC3 and KCC1 are potassium chloride transporters encoded by SLC12A6 and SLC12A4 respectively with partially overlapping function, and KCC3 knockout mice exhibit hypertension." (PMID 28748545, 2017).
neuropathy (4 papers, 2013 to 2026). A disorder affecting the nervous system that manifests with pain, tingling, numbness, and/or muscle weakness. "In humans, mutations in the SLC12A6 gene are generally associated with neuropathy, but there is no known connection between mutations in this gene and obesity-related traits, except for one genome-wide association study signal for BMI." (PMID 37799139, 2023).
agenesis of the corpus callosum with peripheral neuropathy (2 papers, 2013 to 2019). Corpus callosum agenesis-neuropathy is a neurodegenerative disorder characterized by severe progressive sensorimotor neuropathy beginning in infancy with resulting hypotonia, areflexia, amyotrophy and variable degrees of dysgenesis of the corpus callosum. "Mutations in SLC12A6, the gene which encodes for the K–Cl cotransporter-3 (KCC3), results in a rare autosomal recessive neurological disorder known as Hereditary Motor and Sensory Neuropathy/Agenesis of the Corpus Callosum (HSMN/ACC) (OMIM 218000;)." (PMID 23593405, 2013).
epilepsy (2 papers, 2019 to 2022). A brain disorder characterized by episodes of abnormally increased neuronal discharge resulting in transient episodes of sensory or motor neurological dysfunction, or psychic dysfunction. "Mutations in SLC12A5 or SLC12A6, which encode KCC2 and KCC3, respectively, can cause brain disorders such as epilepsy, seizures, and sensorimotor neuropathy with agenesis of corpus callosum." (PMID 36557113, 2022).
Obesity (2 papers, 2016 to 2023). Accumulation of substantial excess body fat. "Similarly, the deletion within the SLC12A6 gene increases the risk of obesity." (PMID 37799139, 2023). "We have demonstrated that deletions in or near the SLC12A6 (Solute Carrier Family 12 Member 6) and RYR3 (Ryanodine Receptor 3) genes are statistically associated with decreased body weight and a lower risk of obesity." (PMID 37799139, 2023).
Alagille syndrome (1 paper, 2025). "Other diagnoses included conditions like Alagille syndrome (three patients), cholestatic hepatitis, cirrhosis, and rare metabolic disorders such as Niemann-Pick disease (Type C): one case, Na+-independent SLC12A6 mutation syndrome (NISCH) syndrome: one case, and Sanjad Sukati syndrome: one case." (PMID 40470412, 2025).
COVID-19 (1 paper, 2021). A disease caused by infection with severe acute respiratory syndrome coronavirus 2. "The genetic variant associations in RORA, SLC12A6, and SLC6A19 genes were observed in genome-wide association study (GWAS) of COVID-19 susceptibility." (PMID 34512723, 2021). "Three genes—RORA, SLC12A6, and SLC6A19—showed associations with multiple COVID-19 phenotypes." (PMID 34512723, 2021).
developmental delay (1 paper, 2024). "Recessive variants in SLC12A6 cause Aldermann's syndrome, a severe early onset motor predominant peripheral neuropathy associated with variable degrees of agenesis of the corpus callosum and developmental delay." (PMID 39083076, 2024).
hereditary spastic paraplegia (1 paper, 2017). Hereditary spastic paraplegias (HSP) comprise a genetically and clinically heterogeneous group of neurodegenerative disorders characterized by progressive spasticity and hyperreflexia of the lower limbs. "Of note, there are nine genes among these targets that when mutated are known causes for inherited peripheral neuropathies (IPN) and hereditary spastic paraplegia (HSP) (Inf2, Sox10, Wnk1, Med25, Fa2h, Bscl2, Slc12a6, Kif1a and Kif5a)." (PMID 28077174, 2017).
peripheral neuropathy (11 papers, 2011 to 2025). A disorder affecting the peripheral nervous system. "In 2016, a child with a severe and progressive peripheral neuropathy was reported in association with a de novo heterozygous variant in SLC12A6." (PMID 39083076, 2024). "In family 6, two affected individuals were found to have a homozygous frameshift duplication mutation (c.2866dup; p.Ser956PhefsTer27) in the SLC12A6 gene (NM_133647.2), which is associated with agenesis of the corpus callosum with peripheral neuropathy (OMIM 218000)." (PMID 39281811, 2024). "In addition, SLC12A6 codes for the ion transporter KCC3 (K-Cl co transporter) that has been associated with AS among other phenotypes including peripheral neuropathy and agenesis of the corpus callosum in mice." (PMID 38439105, 2024). "SLC12A6 Gene (NM_133647.2): A homozygous one-base pair frameshift insertion mutation (c.2865_2865insT; p.Glu955Asnfs*5) associated with agenesis of the corpus callosum with peripheral neuropathy (OMIM 218000)." (PMID 39281811, 2024). "Mice deficient in solute carrier family 12 member 6 (SLC12A6) showed motor dysfunction, peripheral neuropathy, and sensory motor gating defects." (PMID 32602849, 2020).
cancer (5 papers, 2013 to 2025). A tumor composed of atypical neoplastic, often pleomorphic cells that invade other tissues. "Upregulation of SLC12A6 has been observed in several cancer types and is associated with tumor progression and poor prognosis." (PMID 40424447, 2025).
neurodegenerative disease (2 papers, 2010 to 2013). A disorder of the central nervous system characterized by gradual and progressive loss of neural tissue and neurologic function. "Each region also included key genes associated with addiction (Maoa, Ptprd, and Slit3), psychiatric illnesses (Maoa, Myt1l, Slc12a6, and Slit3), and neurodegenerative diseases (Apba1 and Slc12a6)." (PMID 20808911, 2010).
movement disorder (1 paper, 2023). Neurological conditions resulting in abnormal voluntary or involuntary movement, which may impact the speed, fluency, quality and ease of movement. "Interestingly, the SLC12A6 gene has been studied in both humans and dogs, revealing that truncating variants are responsible for movement disorders, although the phenotypes differ between species." (PMID 37799139, 2023).
SLC12A6 also shares sentences with these, for which no sentence is quoted: tumor (5 papers); cervical carcinoma (4); hereditary motor and sensory neuropathy (3); Hyperglycemia (3); and sensory neuropathy (2); cardiovascular disease (2); deafness (2); hypertension (2); neurological disease (2); ovarian carcinoma (2); Sensorimotor neuropathy (2); sickle cell anaemia (2); acute kidney injury (1); autoimmune hemolytic anemia (1); axonal neuropathy (1); Bestrophinopathy (1); beta thalassemia (1); bleeding disorder (1); blood pressure (1); brain disorder (1); breast carcinoma (1); cardiac hypertrophy (1); channelopathies (1); Charcot-Marie-Tooth disease (1); Cirrhosis (1); esophageal cancer (1); esophageal squamous cell carcinoma (1); factor XI deficiency (1); hearing loss (1); hypohidrotic ectodermal dysplasia (1).
A further 16 diseases each share a sentence with SLC12A6 in 1 paper.